ARG1 (arginase 1)
Diseases named in the same sentence as ARG1 in open-access papers (continued):
Sharing a sentence is not in itself a finding about the gene and the disease.
tumor (continued). "In a prostate cancer model, transcriptomic analysis of the tumor microenvironment revealed an increase in the expression of genes associated with pro-tumorigenic macrophages, such as Arg1 Cd163, Mrc1, Retnla, Lyve1, in aged (20–24 months) compared to young male C57BL/6J mice." (PMID 33441138, 2021). "Additionally, a higher ARG1 mRNA level and tumor stage (S = 4) in the HPV− cohort suggested a high risk for these patients." (PMID 33807310, 2021). "ARG1+ TAMs may promote tumor growth as demonstrated by the fact that MΦ-overexpressing ARG1 enhances tumor cell proliferation, while ARG1-deficient MΦs are associated with reduced tumor size in mice models." (PMID 34476174, 2021). "Similarly, in the nutrient-deprived tumor microenvironment, tumor-derived lactate has been proposed to increase Hif-1α activity in tumor-associated macrophages (TAMs) and thus to upregulate Arg1." (PMID 32396064, 2020). "Other studies indicated that MDSCs and tumor-associated macrophage cells (TAMs) could also produce arginase-1, inducible nitric oxide synthase (iNOS) and reactive oxygen species (ROS) to suppress the proliferation of T cells within the tumor." (PMID 33613544, 2020). "Intriguingly, diminished L-arg concentrations have been shown to induce accumulation of arginase-expressing MDSCs in the tumors after administration of pegylated recombinant ARG1 to tumor-bearing mice indicating potential threats associated with L-arg-depleting therapeutic strategies for cancer." (PMID 32499785, 2020). "Mechanistically, inhibition of PI3Kγ decreased TAM expression of genes associated with immune suppression and tumor angiogenesis (Arg1, Tgfb, Il1b, Il6, Vegfa), and upregulated expression of genes associated with anti-tumor immunity (Il12 and Ifng), suggesting TAM reprogramming." (PMID 33584701, 2020). "In addition, arginase-1 induction and PD-L1 expression by tumor-associated M2-like macrophages can suppress T cell immune responses." (PMID 31546897, 2019). "Moreover, Arg1, a marker of tumour-associated macrophages (TAMs) was found tendentially downregulated in the TU region of the lung of patients with NSCLC." (PMID 30956278, 2019). "Furthermore, we demonstrate that buffering tumour acidosis alters the activation state of TAMs, with a significant reduction in genes such as Arg1 and Cd206 that are usually associated with a tumour-promoting role for this population." (PMID 31417189, 2019). "The activation of immunosuppressive pre-metastatic niche cells in tumor-bearing conditions results in up-regulated expression of immune suppressive factors such as arginase 1 (encoded by Arg1), inducible nitric oxide synthase and Treg cells that inhibit effector T cell function." (PMID 29721156, 2018). "While cellular and molecular immunophenotyping demonstrated a robust reprogramming of both innate and adaptive anti-tumor immunity in response to E7046 + E7777 combination therapy, it also induced expression of genes encoding immunosuppressive molecules such as ido1, arg1, PD-1, PD-L1, and Tim3." (PMID 28920002, 2017). "Interestingly, the effect of selumetinib on Arg1 expression in the tumor is associated with the down-regulation of Cox-2 on day 8, but not on day 1 when only Cox-2 is reduced compared to control." (PMID 28807001, 2017). "Moreover, tumor-derived lactate enhances arginase-1 (ARG1) expression in tumor-associated macrophages (TAMs), hindering T-cell activity and proliferation, inhibiting antitumor immune responses and promoting tumor growth." (PMID 28077918, 2016). "As expected, tumor growth was associated with enhanced expression of Arg1 in total leukocytes." (PMID 27936099, 2016). "As expected, arginase 1 (Arg1, M2 marker) was highly expressed by tumor-associated Gr1+, MG and MP." (PMID 27936099, 2016).
tumor (continued). "The chronic sildenafil administration with the drinking water was reported to cause a significant reduction in the NO production and in the expression of ARG-1 associated with the restoration of tumor-specific CD8 T cell responses and a significantly prolonged survival of tumor-bearing mice." (PMID 27827871, 2016). "From these data, we speculated that IL-11 induction at tumour sites is associated with enhanced expression of arginase-1, VEGF, TGF-β, and IL-10, which may be involved in the suppression of T cell responses in the tumour microenvironment." (PMID 28781374, 2015). "This increase corresponded with a significant decrease in Arginase 1 staining (a M2 marker) and an increase in iNOS staining (a M1 marker), suggesting that loss of Ron signaling due to ligand deletion modifies tumor-associated macrophages toward a pro-inflammatory phenotype." (PMID 25938541, 2015). "Examining the tumor infiltration population, we found not only increased proportion of CD11b+Gr1hi cells in Rip2-deficient animals, but also increased expression of arginase-1 and iNOS, which leads to inhibition of T cells and NK cells, and suggests an intrinsic function of Rip2 in MDSC development." (PMID 24733360, 2014). "STAT1 is one of the pathways in MDSCs activation; Gabrilovich demonstrated that STAT1 activation in tumor-associated macrophages is responsible for the upregulation of inducible nitric oxide synthase (iNOS) and arginase 1 activity in these cells, which results in T-cell suppression." (PMID 23307253, 2013). "These tumor-associated macrophages (TAMs) share many common features with the alternatively activated macrophages, showing a typical M2 marker profile with high expression of C-type lectin receptors, stabilin-1, and Arg-1." (PMID 23316105, 2012). "Furthermore, tumour-associated myeloid populations, including myeloid-derived suppressor cells (MDSCs) and tumour-associated macrophages (TAMs), overexpress arginase-1 (ARG1) and inducible nitric-oxide synthase (iNOS), depleting L-arginine and reshaping the microenvironment toward immune escape." (PMID 41394868, 2025). "In addition, the mRNA level of CD163 and ARG1 (the markers of tumor-associated macrophage) was dramatically decreased in TDM and BMDM after B. thetaiotaomicron mixture, B. thetaiotaomicron culture medium, and acetic acid treatment, but not heat killed B. thetaiotaomicron or control bacteria E.coli." (PMID 38270111, 2024). "The accumulation of ARG1-expressing immunomodulatory cells, including M2-like tumor-associated macrophages, tolerogenic DCs, MDSCs, and Treg cells, in the tumor microenvironment (TME) may suppress antitumor immunity by degrading arginine, thus limiting the availability of this amino acid to T cells." (PMID 35898872, 2022). "Changes in Arg-1 expression may cause metabolic disorders and tumor development." (PMID 34715880, 2021). "Interestingly, it has been demonstrated that CD3ζ chain downregulation caused by tumor‐derived MDSCs overexpressing Arg1 might be more detrimental for CD4+ T cells than CD8+ T cells." (PMID 34037806, 2021). "The expression of ARG1 in small tumors (diameter< 5cm, 9.1%, 4/44) was significantly lower as compared with that in the large tumors (diameter≥ 5cm, 28.3%, 13/46, P=0.020), suggesting that the expression of ARG1 might be associated with tumor growth." (PMID 30320132, 2018). "They secrete high levels of anti-inflammatory and pro-fibrotic factors (e.g., IL-10 and TGF-β) and also express enzymes like arginase-1 (Arg1) that drive polyamine production for tissue repair and tumor growth." (PMID 41597210, 2026). "In addition to glutamine, a study on human CCA tissues found that arginase ARG1 was highly expressed and positively correlated with M2 macrophage infiltration, indicating that arginine metabolism reprogramming also affects the polarization of tumor-associated macrophages." (PMID 41513616, 2026).
tumor (continued). "This review delineates the context-dependent functions of ARG1 across diverse cell types-including tumor cells, immune cells, endothelial cells, keratinocytes, and stem cells." (PMID 41939876, 2026). "We identified doxorubicin as a synergistic partner that, when combined with LEE011, inhibits tumor cell proliferation and suppresses myeloid-specific arginase 1 (ARG1) expression." (PMID 42095207, 2026). "In contrast, M2 macrophages are associated with anti-inflammatory responses, promote tumor growth, and show increased expression of CD206 and arginase-1 (ARG1)." (PMID 41545338, 2026). "Next, tumor-infiltrating cells from UTUC patients were analyzed for arginase-1 expression in neutrophils and T cell populations." (PMID 40358184, 2025). "It has been reported that lactic acid produced by tumor cells is mediated by a hypoxia-inducible factor (HIF-1α) and that lactate-induced arginase 1 expression in macrophages induces M2-like polarization of macrophages in a melanoma murine tumor model." (PMID 40940867, 2025). "This evidence underscores the critical role of neutrophils, particularly through the expression of PD-L1 and arginase-1, as mediators of tumor-induced T cell suppression." (PMID 40358184, 2025). "In contrast, M2 macrophages are characterized by an anti-inflammatory phenotype and secrete pro-tumor factors, such as arginase 1 (ARG1)." (PMID 41306968, 2025). "ARG1 depletes arginine in the tumour microenvironment, inhibiting T-cell proliferation and function." (PMID 40234383, 2025). "The Apo-A1 level in TTCS or arginase-1 expression in tumor-infiltrating neutrophils is negatively correlated with tumor-infiltrating CD4+ T population." (PMID 40358184, 2025). "MDSCs exert their immunosuppressive function primarily through the secretion of mediators such as ARG1 and iNOS, which inhibit effector cell activity within the tumor microenvironment." (PMID 41010517, 2025). "Immunohistochemistry analysis of CRC mouse tumor tissue showed that NaB decreased the expressions of PD-L1, Arg-1, and iNOS in a concentration-dependent manner." (PMID 41251471, 2025). "Microglia present in the tumour microenvironment can suppress the immune response from the production of arginase 1 (Arg1) and pro-inflammatory and proliferative microglia have the potential to drive the progression of GBM." (PMID 39795214, 2025). "MDSCs inhibit T cell activation and promote tumor immune evasion through upregulation of ARG-1 expression, secretion of immunosuppressive factors, and expression of inhibitory ligands." (PMID 40452834, 2025). "Simultaneously, STAT6 drives the expression of arginase-1 (ARG1), an enzyme that depletes arginine from the tumor microenvironment." (PMID 40270603, 2025). "Our findings demonstrate that UTUC secreted tumor-derived factors, with apolipoprotein A1 (Apo-A1) being the predominant factor, which upregulated arginase-1 expression in neutrophils." (PMID 40358184, 2025). "Arginase-1 expression supports tumor growth through the production of polyamines, which are important for cell growth, and by out-competing iNOS to prevent the production of pro-inflammatory nitric oxide." (PMID 40282397, 2025). "These M2-TAMs secrete various immunosuppressive factors (e.g., Arg1, IL-10) that enhance tumor cell migration and invasion while fostering an immunosuppressive milieu." (PMID 41585886, 2025). "MDSCs suppress T-cell activation and promote tumour progression by secreting immunosuppressive molecules, such as arginase-1 (Arg1) and inducible nitric oxide synthase (iNOS)." (PMID 40861435, 2025). "When exhibiting a pro-tumor M2 phenotype, TAMs are characterized by high levels of arginase 1 (ARG1), which depletes L-arginine within the TME, thus effectively suppressing CD8+ T cell activation through arginine metabolism." (PMID 40430260, 2025).
tumor (continued). "Arginine acts as a crucial precursor for polyamine biosynthesis, and targeting key metabolic enzymes like arginase-1 (Arg1) can effectively regulate polyamine production in the tumor microenvironment (TME)." (PMID 40438606, 2025). "M1-polarized macrophages, characterized by NOS2 expression, promote tumor suppression through pro-inflammatory activity, whereas M2-like macrophages, which often express ARG1, contribute to immune suppression, matrix remodeling, and therapeutic resistance." (PMID 41573553, 2025). "Th2 cells primarily secrete IL-4, IL-6, and IL-10; IL-4 regulates MDSCs by synthesizing arginase 1 (Arg1) and decomposing l-arginine to induce T-cell apoptosis and tumor immunosuppressive effects." (PMID 41278263, 2025). "In terms of neutrophil activation, proportions of MPO+ and arginase 1+ neutrophils were higher in ascites than in tumor, with a 1.4- to 2.6-fold change, respectively." (PMID 41221283, 2025). "They suppress anti-tumor T cell activity via the secretion of arginase-1, inducible nitric oxide synthase (iNOS), and reactive oxygen species (ROS)." (PMID 41246306, 2025). "This acceleration led to an increase in both tumor volume and weight, alongside a notable enhancement in ARG1 expression within tumor‐infiltrating MDSCs." (PMID 41020041, 2025). "M2 expresses high levels of CD163, CD206, CCL18, and CCL22, releasing anti-inflammatory (TGF-β, IL-4, and IL-13) and inflammatory (IL-6, IL-12, and TNF-α) factors, as well as tumor-promoting arginase-1 and VEGF, modulated by TME signals." (PMID 40940877, 2025). "On the other hand, the M2 type that has been known to be anti-inflammatory and immunosuppressive and tumor-associated macrophages (TAM) as well were assessed using immunohistochemical analysis of CD163, in addition to the genetic expression of Arg1 and Fizz1." (PMID 39949667, 2025). "Tmem119+Arg1+ cells were rarely observed in the tumor core in either vehicle- or peptide-treated mice." (PMID 40281508, 2025). "These resistant TAMs preferentially express angiogenic (VEGFA) and immunosuppressive (CD274, ARG1) genes and promote tumor vascularization." (PMID 41450739, 2025). "In immune cells, particularly tumor-associated macrophages, this NDRG3–Raf–ERK axis complements cytokine signaling and contributes to metabolic polarization by enhancing Arg1 and Vegfa expression in lactate-rich, hypoxic tumor regions." (PMID 40710349, 2025). "MDSCs secrete high NO, Arg1, iNOS, and ROS concentrations, which inhibit immune cells in the TME, especially T cells, promote tumor cell growth, and cause tumor immune escape." (PMID 39759114, 2025). "Consistently, at the protein level, BBR markedly suppressed tumor-conditioned medium-induced upregulation of Arg-1 and Retnla." (PMID 41585886, 2025). "The assessment of markers associated with immune-suppressive activities in splenic granulocytes (CD11b+Ly6G+) showed elevated mRNA levels of Il10, Vegfa, Tgfb1, and Arg1 in the tumor-bearing vehicle-control group compared to naïve mice." (PMID 41282257, 2025). "The secretion of Arg1 by MDSCs results in the deprivation of the tumor microenvironment of L-arginine, which in turn leads to the downregulation of the TCR-ζ chain." (PMID 40356601, 2025). "Concurrently, they establish an immunosuppressive microenvironment through arginase-1-mediated arginine depletion, which impairs T-cell function, and recruit tumor-promoting macrophages and Tregs, fostering tumor growth and sorafenib resistance." (PMID 41438763, 2025). "Anti-tumor responses are also negatively influenced by the enhancement of M2 polarization by inducing arginase-1 (ARG-1), transcriptional repressors, HIF-1α and IL-6 via the upregulation of MCT-4 expression and glycolytic rate promoted by lactate." (PMID 40092297, 2025). "For example, ARG1 drives tumor immune suppression by consuming Arg and inhibiting T cell activation." (PMID 41281760, 2025).
tumor (continued). "Our in vivo studies revealed that HCC/macrophage co-xenografts exhibited accelerated growth with enhanced M2 polarization, evidenced by an increased number of CD163+/Arg-1+ macrophages in tumor." (PMID 40453717, 2025). "Conversely, M2 macrophages promote immunosuppression via IL-10, TGF-β, and arginase-1 (Arg-1) expression, facilitating tissue repair, angiogenesis, and tumor progression." (PMID 40563359, 2025). "Second, these macrophages release a spectrum of immunoregulatory factors such as TGF-β, IL-10, Arg-1, and nitric oxide (NO) which sustain an immunosuppressive microenvironment conducive to tumor expansion." (PMID 41058699, 2025). "Simultaneously, tumor cells downregulate enzymes that break down arginine into polyamines (e.g., ARG1) to accumulate high intracellular levels of arginine." (PMID 41293169, 2025). "In contrast, anti-inflammatory Spp1+/Arg1+ macrophages, devoid of immunostimulatory functions, cluster near necrotic cores, underscoring the significance of the “functional tumor geography”." (PMID 41176316, 2025). "In vitro, BBR suppressed IL-4 or tumor cell supernatant-induced M2 polarization, as evidenced by decreased expression of M2 polarization marker genes (Arg1, Retnla, etc.)and reduced JAK1/STAT6 phosphorylation levels." (PMID 41585886, 2025). "Considering the interplay between systemic immune cell ratios and the tumor microenvironment, particularly their association with the NOS2/ARG1 axis and tumor-infiltrating lymphocytes, we next explored the clinical relevance of these markers." (PMID 41573553, 2025). "Lipid uptake by tumor-derived macrophages has been shown to result in M2 polarization and an anti-inflammatory phenotype via activation of Arg1 expression." (PMID 39941714, 2025). "The expression of ARG1 in tumors has been observed to increase with tumor grade and reflects lymph node involvement, indicating a potential role in disease progression." (PMID 41268067, 2025). "MDSCs diminish anti-tumor immunity, particularly T cell activity, by secreting substances like arginase-1 (Arg-1), inducible nitric oxide synthase (iNOS), and reactive oxygen species (ROS)." (PMID 40534850, 2025). "CXCL2 and IL-13 play crucial roles in promoting neutrophil recruitment and upregulating arginase-1 (Arg1), which suppresses T-cell activation and aids tumor progression." (PMID 40387965, 2025). "Accordingly, it increased levels of CD204, CD206 and ARG1 in human tumor-conditioned macrophages, while decreasing HLA-DR levels." (PMID 40588561, 2025). "In contrast, N2 neutrophils are known to release high levels of ARG-1, which suppresses T-cell function within tumours." (PMID 41573639, 2025). "This dual action not only enhances antitumor immunity but also exerts significant inhibitory effects on tumor growth in vivo, highlighting a promising strategy to overcome ARG1-mediated immunosuppression." (PMID 41573553, 2025). "While N1 marker expression remained stable, Neu2 (differentiation end) exhibited mild up-regulation of N2-associated markers, including ARG1, VEGFA, and CCL2, consistent with an immunosuppressive, tumor-promoting phenotype." (PMID 40959269, 2025). "have developed surface-engineered macrophages capable of trimeric TRAIL (Tri-TRAIL-iM) through induction by a tumor-conditioned specific promoter, Arg1, within the TME." (PMID 40110051, 2025). "In this study, tumor-conditioned medium derived from PC-3 cells induced M2 macrophage polarization, as evidenced by increased expression of M2 phenotype markers such as Arg1, CD206, and CD163." (PMID 41019043, 2025). "Blocking MFG-E8 or integrin β3 promotes microglia pro-inflammatory polarization, reduces ARG-1 expression, and limits tumor growth." (PMID 40427130, 2025). "It is worth noting that ARG1 in human is stored in an inactive state within the granules of neutrophils and becomes activated upon release.IL-8 secreted by NSCLC tumor cells promotes the extracellular release of ARG1 from infiltrating neutrophils." (PMID 41254689, 2025).